MARCO (macrophage receptor with collagenous structure)
Description:
Pattern recognition receptor (PRR) which binds Gram-positive and Gram-negative bacteria. Also plays a role in binding of unopsonized particles by alveolar macrophages (By similarity). Binds to the secretoglobin SCGB3A2.
Synonyms: SCARA2; SR-A6
Tractability: Antibody: UniProt places it where antibodies can reach, with high confidence; its Gene Ontology location is reachable by antibodies, with high confidence; UniProt predicts a signal peptide or a membrane-spanning region.
Gene: Protein-coding gene on chromosome 2 (118,942,172 to 118,994,664, forward strand). Ensembl gene ENSG00000019169.
Subcellular location: Cell membrane
Subcellular location (Human Protein Atlas): Golgi apparatus; Vesicles
Pathways (Reactome):
Vesicle-mediated transport: Scavenging by Class A Receptors
Gene Ontology:
Molecular function: G protein-coupled receptor binding; amyloid-beta binding; cargo receptor activity; pattern recognition receptor activity; transmembrane signaling receptor activity
Biological process: adenylate cyclase-inhibiting G protein-coupled receptor signaling pathway; amyloid-beta clearance; cell surface receptor signaling pathway; extracellular matrix organization; phagocytosis, engulfment; positive regulation of ERK1 and ERK2 cascade; receptor-mediated endocytosis
Cellular component: cytoplasm; endocytic vesicle membrane; plasma membrane; membrane
Genetic constraint (gnomAD): Loss-of-function variants: 59 observed, 63.98 expected, observed/expected ratio (o/e) 0.92, 90% interval 0.75 to 1.14. The upper end of that interval is the gene's LOEUF score, 1.14, which puts it in group 5 of 6, group 1 being the genes least tolerant of losing a copy. Missense variants: 666 observed, 640.9 expected, observed/expected ratio (o/e) 1.04, 90% interval 0.97 to 1.11. Synonymous variants: 264 observed, 239.55 expected, observed/expected ratio (o/e) 1.1, 90% interval 1 to 1.22.
Homologues: Orthologues: chimpanzee MARCO (98% identical), macaque MARCO (92% identical), mouse Marco (68% identical), rat Marco (67% identical), rabbit MARCO (66% identical), dog MARCO (65% identical), guinea pig MARCO (63% identical), pig MARCO (52% identical). Paralogues in human: SCARA5 (22% identical), MSR1 (21% identical), COLEC12 (21% identical).
Diseases named in the same sentence as MARCO in open-access papers:
MARCO is named in the same sentence as 133 diseases in open-access papers, as found by Europe PMC text mining. Sharing a sentence is not in itself a finding about the gene and the disease. The quoted sentences say what the papers report.
melanoma (25 papers, 2013 to 2025). A malignant, usually aggressive tumor composed of atypical, neoplastic melanocytes. "Previous studies have implicated MARCO as an unfavorable marker in melanoma and non-small cell lung cancer; here, we find that bulk MARCO expression is associated with worse prognosis and mesenchymal subtype." (PMID 34011400, 2021). "In our study, vaccination with tumor lysate pulsed, MARCO-deficient DC led to enhanced anti-tumor T cell activity and regression of B16 melanoma." (PMID 23840879, 2013). "Blocking MARCO in a syngeneic melanoma tumour model also reduces the suppressive effects of TAMs on NK cells and enhances the efficacy of T cell-focussed immunotherapies, such as PD-1/PD-L1 inhibitors." (PMID 40385641, 2025). "Here, we demonstrated that 2L4-8, a novel MARCO monoclonal antibody, effectively suppresses tumor growth in a murine E0771 breast cancer model and B16-F10 melanoma model." (PMID 40695812, 2025). "In vitro studies have shown that antibodies to MARCO promote glycolysis and exhibit the ability to inhibit tumour growth and metastasis in experimental breast cancer and melanoma models." (PMID 40385641, 2025). "Accordingly, the combination of anti-CTLA-4 and anti-MARCO has been shown to increase the efficacy of melanoma and colon cancer treatment." (PMID 40385641, 2025). "Separate models (melanoma) have found that the injection of anti-MARCO antibodies into tumor-bearing mice leads to an influx of NK cells and CD8+ T cells, and this effect is augmented by the addition of anti-PD-L1 antibodies." (PMID 36031601, 2022). "Application of antibodies against MARCO resulted in the reduction of tumor growth and inhibition of metastasis in murine models for melanoma and breast cancer." (PMID 36686729, 2022). "We also demonstrated that MARCO-expressing macrophages are present in human breast cancer, malignant melanoma, periampullary adenocarcinoma, and lung cancer." (PMID 36310582, 2022). "It has been shown that targeting the scavenger receptor MARCO with antibodies reduces tumor growth and metastasis in murine tumor models of melanoma, colon cancer, and breast cancer." (PMID 35962453, 2022). "We previously demonstrated in mice that targeting the scavenger receptor (SR) MARCO (macrophage receptor with collagenous structure) in experimental melanoma, colon and breast cancer mouse models reduces tumor growth and impairs metastasis in breast cancer." (PMID 36310582, 2022). "In a mouse model of melanoma, treatment with anti-MARCO reversed the inhibitory effect of TAMs on NK cells and synergized with T cell immunotherapy to enhance the treatment efficacy of melanoma." (PMID 36510315, 2022). "While these recruitment factors are potential targets, MARCO itself also presents a promising target—anti-MARCO therapeutic antibodies have demonstrated efficacy in mouse melanoma models." (PMID 34011400, 2021). "MARCO antibody alters macrophage polarization, enhancing NK cell activation and tumor killing, and the anti-tumor effect of MARCO antibody in combination with PD-1/L1 antibody is more potent in a mouse model of melanoma." (PMID 34778091, 2021). "In solid tumor models (melanoma, breast cancer, and colon carcinoma), pattern recognition scavenger receptor MARCO defined immunosuppressive TAMs." (PMID 33648605, 2021). "Although the expression of MARCO in testicular cancer, cervical cancer, melanoma, thyroid cancer, brain cancer, and renal cancer increase, there are fewer fold changes than in pancreatic cancer." (PMID 34778091, 2021). "Although the expression of MARCO in testicular cancer, cervical cancer, melanoma, thyroid cancer, brain cancer, and renal cancer increased, there were fewer fold changes than in pancreatic cancer." (PMID 34778091, 2021). "For example, it was recently demonstrated that antibody targeting of MARCO-expressing TAMs blocked tumor growth and metastasis, and also enhanced the effects of immune checkpoint therapy in melanoma and colon carcinoma models." (PMID 31779710, 2019).
melanoma (continued). "For example, in mice with melanoma established by subcutaneous injection of B16 cells, an anti-MARCO monoclonal antibody treatment enhances the efficacy of anti-CTLA4 antibody treatment in suppressing tumor growth." (PMID 29670880, 2018). "For example, a monoclonal antibody targeted to the scavenger receptor MARCO was shown to reprogram TAMs into M1-like macrophages, inducing anti-tumor activity (in models of breast cancer, colon carcinoma, and melanoma) and enhancing the efficacy of immune checkpoint therapy." (PMID 38545103, 2024). "Similarly, experiments revealed that anti-Human MARCO antibody reactivated NK cell-mediated melanoma killing." (PMID 36510315, 2022). "Interestingly, targeting MARCO‐positive TAMs with a specific antibody reduces tumor growth and metastasis in breast, colon, and melanoma mouse models." (PMID 34060699, 2021). "Importantly, preclinical studies have demonstrated that an anti-MARCO antibody inhibits tumor growth and metastasis in 4T1 mammary carcinoma and B16 melanoma mouse models." (PMID 34778091, 2021). "Anti-MARCO immunotherapy could synergistically enhance the effect of checkpoint inhibitor (anti-CTLA4) in B16 melanoma models." (PMID 32756500, 2020). "Likewise, combination of an anti-MARCO with an anti-CTLA4 antibody was investigated in mouse model of melanoma." (PMID 30577495, 2018). "In the B16 tumors as well as human melanoma samples, MARCO is predominantly expressed by TAM." (PMID 29670880, 2018). "Gene expression of CD36, MARCO, and various FABP isoforms in 355 patients (208 patients with melanoma versus 147 healthy skin controls) was analyzed, according to the transcriptome expression data reported in the IST Online database." (PMID 32209538, 2020). "The expression of CD36, MARCO, FABP4, FABP6, and FABP7 in melanoma samples and healthy skin biopsies is visualized, according to data retrieved from the IST Online database." (PMID 32209538, 2020). "Notably, MARCO, a key protein within a subset of macrophages that are involved in phagocytosis, inflammation, and others, has been implicated as a new immune target for anti-TAM treatment for treating various solid tumors, including non-small-cell lung carcinoma, melanoma, and breast cancer." (PMID 32847614, 2020). "Similarly, the antibody targeting macrophage receptor with the collagenous structure (MARCO), by crosslinking the inhibitory FcgRIIB on TAMs, synergistically increases anti-CTLA4 immunotherapy in melanoma and colon cancer mouse models." (PMID 34476174, 2021). "Anti-MARCO treatment potently repolarised TAMs in an FcγRIIb-dependent manner and in combination with anti-CTLA4 immunotherapy showed enhanced anti-tumour effects in mouse models of melanoma and colon carcinoma." (PMID 30577495, 2018). "After subcutaneous injection into mice, MARCO-/- TP-DCs migrated more efficiently to the draining lymph node leading to enhanced generation of tumor-specific IFN-γ producing T cells and improved tumor regression and survival in B16 melanoma-bearing mice." (PMID 23840879, 2013). "Moreover, several preclinical models including melanoma, breast and CRC have demonstrated that anti-MARCO monoclonal antibodies not only reduce tumor volumes, but also appear to convert MARCO-expressing TAMs from an M2 to an M1 phenotype while also reducing Treg levels." (PMID 36031601, 2022).
breast carcinoma (18 papers, 2016 to 2025). "MARCO has further been revealed to be a gene overexpressed in the tumor microenvironment and linked to poor prognosis in breast cancer." (PMID 41301877, 2025). "In summary, macrophages were the major immune cells in breast adipose tissue and breast cancer leads to a marked increase in the proportion of MARCO+PLAUR+ and lipid-associated macrophages." (PMID 37153595, 2023). "MARCO was reported to be associated with M2 phenotype and was linked to poorer outcomes in human breast cancer." (PMID 33429363, 2021). "MARCO is a class A scavenger receptor expressed by immune‐suppressive tumor‐associated macrophages and has been linked to poor prognosis in breast cancer." (PMID 34060699, 2021). "Previous studies indicate that downregulation of CXCL14 is associated with prognosis in gastric cancer patients, MT1X may aid in the prognostic discrimination of oral squamous cell carcinoma cases, and MARCO expression is associated with breast cancer survival and risk of recurrence." (PMID 27567667, 2016). "Genetic ablation of MARCO in a murine breast cancer model attenuated tumor growth, accompanied by reduced monocytic MDSCs (M-MDSCs) and total tumor-associated macrophages (TAMs), along with enhanced infiltration of CD8+ T cells and natural killer (NK) cells." (PMID 40695812, 2025). "It has been reported that MARCO plays a role in M2 macrophage infiltration in the tumor tissue and affects the prognosis of breast cancer." (PMID 40695812, 2025). "Clinical studies across multiple cancer types, including pancreatic ductal adenocarcinoma (PDAC), colon cancer, and breast cancer, have consistently demonstrated that increased infiltration of MARCO+ TAMs correlates with poor patient prognosis." (PMID 40695812, 2025). "More importantly, in a murine breast cancer model, the MARCO downregulating antibody exhibited significant anti-tumor activity and synergized with PD-1 blockade." (PMID 40695812, 2025). "In the present study, we provide direct evidence of MARCO expression in MDSCs, particularly the monocytic subset (M-MDSCs) in human breast cancer." (PMID 40695812, 2025). "We previously identified a subpopulation of MARCO- expressing macrophages highly represented in the TME in human breast cancer, metastatic melanoma, periampullary adenocarcinoma (intestinal type), and small cell lung cancer." (PMID 36310582, 2022). "Anti-MARCO mAb arrested tumor growth and lowered metastasis in a mouse 4T1 mammary carcinoma model by reprogramming TAMs." (PMID 34976826, 2021). "MARCO-expressing macrophages are present in the tumor microenvironment in human breast cancer, metastatic melanoma, periampullary adenocarcinoma of the intestine, and non-small-cell lung cancer." (PMID 34778091, 2021). "Although MARCO has been previously reported as a pro-tumor TAM marker in non-small cell lung cancer, lung adenocarcinoma, and breast cancer, and has been associated with poor prognosis in periampullary adenocarcinoma, its role has not been previously reported in GBM." (PMID 34011400, 2021). "MARCO is expressed by TAMs in human breast cancer and correlated with poor clinical outcome." (PMID 34976826, 2021). "Here, we identify macrophage receptor with collagenous structure (MARCO) as a critical regulator of MDSC differentiation and immunosuppression in breast cancer." (PMID 40695812, 2025). "Transcriptomic analysis revealed upregulation of macrophage activation markers, genes such as S100A8, S100A2, KRT81, KRT6C, MARCO and MMP1, as well as processes related to keratinization and the formation of a cornified envelope in breast cancer cells." (PMID 41073799, 2025). "Using breast cancer-derived exosomes to induce murine bone marrow or human PBMC, we observed that TDEs not only enhanced MDSC differentiation but also upregulated MARCO expression." (PMID 40695812, 2025).
breast carcinoma (continued). "The current data identified the high level of MARCO+PLAUR+ macrophages in adipose tissue adjacent to tumors at single cell level, indicating MARCO+PLAUR+ macrophages were related to the progression of breast cancer." (PMID 37153595, 2023). "ScRNA-seq data of the current study indicated increased MARCO+ and CD36+ macrophage subpopulations with immunosuppressive functions in breast cancer." (PMID 37153595, 2023). "Previously published results demonstrated that the expression of MARCO correlated with expression of M2 markers expressed by tumor-promoting macrophages and EMT-metastasis-driving gene signatures in breast cancer, and antibody targeting of MARCO-expression TAMs blocked tumor growth and metastasis." (PMID 37153595, 2023). "Despite the fact that MARCO has already been found to be a marker for pro‐tumorigenic TAMs in NSCLC, breast cancer, and GBM, its role in RCC has not been thoroughly documented previously." (PMID 41117057, 2025).
colon carcinoma (12 papers, 2018 to 2024). "Targeting MARCO with a monoclonal antibody in murine breast and colon cancer models reprograms TAMs toward a pro-inflammatory phenotype." (PMID 36310582, 2022). "MARCO has also been examined in preclinical mouse colon cancer models with the observation that MARCO expression defined a subtype of suppressive tumor-associated macrophages (TAMs)." (PMID 30348985, 2018). "Treatment of breast and colon carcinoma mouse models with an anti-MARCO monoclonal antibody reprogrammed TAMs to a pro-inflammatory phenotype and increased tumor immunogenicity, suggesting that targeting MARCO in TAMs represents a promising mode of cancer treatment." (PMID 32509781, 2020). "GeoMX DSP-NGS analysis of colon cancer patients identified the correlation of PFKFB3 expression with monocytes infiltration and M2-type polarization markers, including CD163, CD206, CD204 and MARCO." (PMID 36733385, 2022).
lung carcinoma (11 papers, 2020 to 2026). "In a non-small cell, lung cancer model, it was demonstrated that an accumulation of MARCO-expressing macrophages is associated with worse clinical outcomes and resistance to anticancer therapy." (PMID 34572315, 2021). "In lung cancer, targeting MARCO on immunosuppressive macrophages has shown promise, hindered regulatory T cells while bolstering cytotoxic lymphocyte functions." (PMID 39494300, 2024). "The phenotype of tumor-associated macrophages in lung cancer is characterized by M2 class markers, such as CD163, CD204, and MARCO, which are transmembrane receptors." (PMID 35369515, 2022). "For example, lung cancer cells were found to promote M2 polarization through the release of IL-37, leading to macrophage expression of MARCO (macrophage receptor with collagenous structure) and the induction of tumor-promoting phenotypes." (PMID 33924237, 2021). "MARCO was defined as one more M2 marker of TAMs in lung cancer." (PMID 33194645, 2020). "TAM phenotype in lung cancer is characterized mostly by M2-like markers, such as CD163, CD204, and MARCO." (PMID 33194645, 2020). "Indeed, antibody-mediated blockade of MARCO and IL-37R, or CRISPR knockout of IL-37 in lung cancer cells, altered TAM phenotypes, resulting in reduced activity of regulatory T cells and enhanced cytotoxic function of both NK and T cells." (PMID 33924237, 2021).
hepatocellular carcinoma (10 papers, 2017 to 2025). A malignant tumor that arises from hepatocytes. "High expression of MARCO in TAMs from the tumor tissues was associated with increased OS in patients with hepatocellular carcinoma (HCC)." (PMID 36686729, 2022). "One previous study on hepatocellular cancer showed that decreased expression of MARCO was associated with poor prognosis, however, in contrast to the present study, that study did not look at immune cell specific expression of MARCO, but rather at intra-tumoural MARCO expression." (PMID 28673320, 2017). "In cases of hepatocellular carcinoma, MARCO was among the top 30 differentially expressed genes when comparing cancerous tissues to adjacent non-cancerous tissues." (PMID 40565155, 2025). "However, the association of decreased MARCO expression by macrophages with tumor progression and poor prognosis in human hepatocellular carcinoma (HCC) was also observed." (PMID 34778091, 2021). "Although the role of MARCO in AIH is still unclear, MARCO participates in part development of hepatocellular carcinoma." (PMID 36282897, 2022).